PRSS27 (serine protease 27)
Synonyms: MPN; CAPH2
Tractability: Antibody: UniProt places it where antibodies can reach, with medium confidence; UniProt predicts a signal peptide or a membrane-spanning region; its Gene Ontology location is reachable by antibodies, with medium confidence.
Target class: Enzyme; Hydrolase
Gene: Protein-coding gene on chromosome 16 (2,712,419 to 2,721,166, reverse strand). Ensembl gene ENSG00000172382.
Subcellular location: Secreted
Subcellular location (Human Protein Atlas): Vesicles; Predicted to be secreted
Gene Ontology:
Molecular function: serine-type peptidase activity; serine-type endopeptidase activity
Biological process: protein processing; proteolysis
Cellular component: extracellular region; plasma membrane
Genetic constraint (gnomAD): Loss-of-function variants: 27 observed, 27.72 expected, observed/expected ratio (o/e) 0.97, 90% interval 0.72 to 1.34. The upper end of that interval is the gene's LOEUF score, 1.34, which puts it in group 5 of 6, group 1 being the genes least tolerant of losing a copy. Missense variants: 401 observed, 364.06 expected, observed/expected ratio (o/e) 1.1, 90% interval 1.01 to 1.2. Synonymous variants: 178 observed, 157.58 expected, observed/expected ratio (o/e) 1.13, 90% interval 1 to 1.28.
Homologues: Orthologues: chimpanzee PRSS27 (98% identical), macaque PRSS27 (92% identical), dog PRSS27 (83% identical), pig PRSS27 (80% identical), guinea pig PRSS27 (77% identical), mouse Prss27 (76% identical), rat Prss27 (75% identical), rabbit PRSS27 (63% identical). Paralogues in human: PRSS33 (46% identical), PRSS48 (38% identical), PLG (33% identical), TMPRSS12 (31% identical), OVCH1 (30% identical), PLAT (29% identical), PRSS50 (28% identical), KLK9 (27% identical), KLK15 (27% identical), GZMM (26% identical), PRSS57 (24% identical), PRSS37 (20% identical), and 2 more.
Diseases named in the same sentence as PRSS27 in open-access papers:
PRSS27 is named in the same sentence as 6 diseases in open-access papers, as found by Europe PMC text mining. Sharing a sentence is not in itself a finding about the gene and the disease. The quoted sentences say what the papers report.
Allergy (1 paper, 2023). An allergy is an immune response or reaction to substances that are usually not harmful. "The levels of FS (Follistatin), Erb-B2 receptor tyrosine kinase 2 (ERBB2), TGFR2 (transforming growth factor beta receptor 2), MSLN (mesothelin) and TM (thrombomodulin) were influenced by Benzodiazepines and PRS27 (serine protease 27) by allergy drugs." (PMID 37667404, 2023).
tumor (3 papers, 2017 to 2023). "Additionally, we observed that clusters 6, 7, 9 and 13 (CASP14, PRSS27, CALML5), which were enriched in CC, manifested high expression levels of genes related to carcinogenic pathways such as epithelial‐to‐mesenchymal transition, tumour cell proliferation, migration, invasion and angiogenesis." (PMID 36967539, 2023).
cancer (1 paper, 2017). A tumor composed of atypical neoplastic, often pleomorphic cells that invade other tissues. "PITX1, CST6 and HOPX were reported their downregulation in various types of human cancer, and PRSS27 was known to be highly expressed in nonkeratinizing stratified squamous epithelia of human esophagus and its dysregulation was supposed to be related to characteristics of carcinoma." (PMID 29137437, 2017).
PRSS27 also shares sentences with these, for which no sentence is quoted: preeclampsia (1 paper); psoriasis (1); Tinnitus (1).